RNY3P12 (RNY3 pseudogene 12)
Gene: Miscellaneous RNA gene on chromosome 10 (92,334,463 to 92,334,564, forward strand). Ensembl gene ENSG00000202297.
Homologues: Orthologues: chimpanzee Y_RNA (100% identical), macaque Y_RNA (95% identical). Paralogues in human: Y_RNA (86% identical), Y_RNA (85% identical), Y_RNA (84% identical), RNY3 (83% identical), Y_RNA (82% identical), RNY3P1 (81% identical), Y_RNA (81% identical), Y_RNA (80% identical), Y_RNA (79% identical), Y_RNA (78% identical), RNY3P11 (77% identical), RNY3P13 (77% identical), and 91 more.